MSANTD2 (Myb/SANT DNA binding domain containing 2)
Synonyms: C11orf61; FLJ23342
Tractability: PROTAC: UniProt records ubiquitination sites on it; ubiquitination databases record sites on it.
Gene: Protein-coding gene on chromosome 11 (124,766,498 to 124,800,706, reverse strand). Ensembl gene ENSG00000120458.
Subcellular location (Human Protein Atlas): Mitochondria
Genetic constraint (gnomAD): Loss-of-function variants: 19 observed, 44.31 expected, observed/expected ratio (o/e) 0.43, 90% interval 0.3 to 0.63. The upper end of that interval is the gene's LOEUF score, 0.63, which puts it in group 2 of 6, group 1 being the genes least tolerant of losing a copy. Missense variants: 540 observed, 641.16 expected, observed/expected ratio (o/e) 0.84, 90% interval 0.78 to 0.9. Synonymous variants: 287 observed, 254.92 expected, observed/expected ratio (o/e) 1.13, 90% interval 1.02 to 1.24.
Homologues: Orthologues: macaque MSANTD2 (99% identical), rabbit MSANTD2 (99% identical), dog MSANTD2 (98% identical), mouse Msantd2 (97% identical), rat Msantd2 (97% identical), chimpanzee MSANTD2 (95% identical), pig MSANTD2 (89% identical), tropical clawed frog msantd2 (75% identical), zebrafish MSANTD2 (64% identical), guinea pig MSANTD2 (61% identical). Paralogues in human: UTF1 (13% identical), MSANTD7 (13% identical).
Diseases named in the same sentence as MSANTD2 in open-access papers:
MSANTD2 is named in the same sentence as 6 diseases in open-access papers, as found by Europe PMC text mining. Sharing a sentence is not in itself a finding about the gene and the disease. The quoted sentences say what the papers report.
autism (1 paper, 2023). Persistent deficits in social interaction and communication and interaction as well as a markedly restricted repertoire of activity and interest as well as repetitive patterns of behavior. "LncRNA BCLET is the antisense RNA of MSANTD2, which is also known as C11orf61 and is significantly enriched in autism‐related postzygotic mutations in whole‐exome sequences." (PMID 37211917, 2023).
bladder (1 paper, 2023). "Mechanistically, BCLET recognized and regulated AS of MSANTD2 to participate in bladder carcinogenesis, preferentially promoting the production of MSANTD2‐004." (PMID 37211917, 2023).
bladder cancer (1 paper, 2023). "LncRNA BCLET is involved in tumorigenesis by suppressing the malignant phenotype of bladder cancer through AS of MSANTD2 to preferentially produce the isoform MSANTD2‐004." (PMID 37211917, 2023). "Coexpression analysis showed that BCLET and MSANTD2‐004 had a significant positive correlation (r = 0.828 for bladder cancer tissues and 0.783 for bladder normal tissues, p < 0.0001)." (PMID 37211917, 2023). "We further explored the biological function of the splicing isoform MSANTD2‐004 in bladder cancer." (PMID 37211917, 2023). "In addition, a novel positive correlation was found between the expression of BCLET and the splicing ratio of MSANTD2‐004 (r = 0.849 for bladder cancer tissues and 0.761 for normal bladder tissues, respectively, p < 0.0001)." (PMID 37211917, 2023).
breast carcinoma (1 paper, 2021). "Dysregulation of EGFR expression and signaling was previously well documented to contribute to the progression and metastasis of breast cancer while MSANTD2 played a crucial role in decreased epidermal growth factor endocytosis." (PMID 34627275, 2021).
tumor (2 papers, 2021 to 2023). "The tumor tissues overexpressing BCLET‐long/BCLET‐short showed significantly reduced expression of the proliferation marker Ki67 and notably increased expression of MSANTD2, a gene located near BCLET." (PMID 37211917, 2023). "In addition, we observe that four genes (i.e., COL9A1, MSANTD2, LMBRD1 and RP11-1391J7.1) were differentially expressed between normal samples and tumor samples, and that COL9A1 was differentially expressed among different tumor stages." (PMID 34627275, 2021).
MSANTD2 also shares sentences with these, for which no sentence is quoted: schizophrenia (1 paper).